CX3CR1 (C-X3-C motif chemokine receptor 1)
Diseases named in the same sentence as CX3CR1 in open-access papers (continued):
Sharing a sentence is not in itself a finding about the gene and the disease.
pulmonary fibrosis (continued). "Given the crucial involvement of BM-derived CX3CR1+ cells in lung fibrosis, we focused on an additional cell type present in the BM, the fibrocytes." (PMID 29203799, 2017). "Notwithstanding that the part of FKN in the lung fibrosis pathogenesis abides ambiguous, lung fibrosis induced by bleomycin in mice was correlated with upregulated expression of CX3CR1 on M2‐type macrophages and fibroblasts, which played a central part in fibrosis." (PMID 39392260, 2024). "The high number of CX3CR1‐expressing cells in lung tissues of SSc patients and lesional skins of those with diffuse cutaneous involvement correlated considerably with the severity of pulmonary fibrosis and erythrocyte sedimentation rates." (PMID 39392260, 2024). "Therefore, to test the functional role of Cx43 in lung fibrosis resulting from injury we used the Cx3cr1-CreERT2, a Cre driver that has been used for functional study of monocyte-derived macrophages in multiple contexts in vivo." (PMID 35634278, 2022). "Therefore, to study the changes and invasion of immune cells mediated by CX3CR1 in the process of pulmonary fibrosis is very helpful for the treatment of IPF." (PMID 35222428, 2022). "Single-cell RNA sequencing characterized the heterogeneity of macrophages in bleomycin-induced pulmonary fibrosis and identified a pathological subgroup of transitional macrophages (CX3CR1 + SiglecF +) required for the fibrotic response to the injurious stimuli." (PMID 33952261, 2021). "Other possibilities could involve the role of CX3CR1+ SiglecF+ macrophages in epithelial–mesenchymal transition believed to contribute to lung fibrosis and the inhibition of NF-κB–mediated profibrotic gene expression induced by CD148 phosphatase in fibroblasts." (PMID 35377803, 2022). "Type I IFN recruits CX3CR1+ M2 macrophages in the lungs by inducing the secretion of CX3CL, and M2 macrophages are responsible for producing tumor growth factor-β to promote pulmonary fibrosis." (PMID 37006269, 2023). "In addition, fibrocytes also express CX3CR1, and their population increases in the lungs of mice with BLM-induced pulmonary fibrosis." (PMID 35155503, 2022). "However, there is still no study for the role of CX3CR1 in idiopathic pulmonary fibrosis (IPF)." (PMID 35222428, 2022). "Although anti-CX3CL1 mAb therapy did not attenuate lung fibrosis in SKG-ILD, the infiltration of BALF M1 macrophages strongly expressing CX3CR1 into the lungs was efficiently suppressed." (PMID 34067842, 2021).
rheumatoid arthritis (24 papers, 2010 to 2025). A chronic, systemic autoimmune disorder characterized by inflammation in the synovial membranes and articular surfaces. "Of note, cluster 3 failed to express the subset of Tph-associated chemokines (e.g., Cxcl13, Ccr2, Cx3cr1) described in rheumatoid arthritis and other conditions, a finding consistent with previous reports that chemokine expression by Tph cells is context dependent." (PMID 39087473, 2024). "Diabetes mellitus and rheumatoid arthritis are systemic diseases that are associated with an increased amount of CX3CL1 and CX3CR1, providing good evidence for their role in the chronic inflammatory process and pathogenesis of bone resorption." (PMID 38590803, 2024). "Higher soluble and membrane-bound levels of CX3CL1 and CX3CR1 have been found in the serum of rheumatoid arthritis patients, suggesting that CX3CL1 is the main factor that drives inflammation through the recruitment of monocytes." (PMID 38590803, 2024). "This systematic review aimed to investigate the role of the Fractalkin‐CX3CL1/CX3CR1 axis as pro‐inflammatory biomarkers to distinguish between periodontitis and rheumatoid arthritis and/or systemically healthy subjects." (PMID 38415821, 2024). "For Scopus, the search strategy was: (“periodontitis”/AND “rheumatoid arthritis”/AND “CX3CL1”/AND “CX3CR1”)." (PMID 38415821, 2024). "Additionally, CX3CR1 expression has been identified in synovial membrane specimens of patients with both osteoarthritis and rheumatoid arthritis." (PMID 41019141, 2025). "Rheumatoid arthritis (RA) is a chronic autoimmune disease and the integrity of CX3CR1+ synovial macrophage barrier significantly impacts its progression." (PMID 40038808, 2025). "More recent studies using healthy and rheumatoid arthritis (RA) synovium have proposed new nomenclature for different synovial macrophage subsets, including CX3CR1+/TREM2+ lining macrophages and subsets based on the expression of CD163, CD206, and MERTK." (PMID 37612718, 2023). "For rheumatoid arthritis, systemic lupus erythematosus, ankylosing spondylitis and osteoarthritis diseases, those common factors include TNFSF10, CX3CR1, LY96, TLR5, TXN, TIA1, PRKCH, and PRF1." (PMID 26352601, 2015). "The CD4+ and CD8+ T cells expressing CX3CR1 predominantly produce IFN-γ and TNF-α, and these T cells infiltrate the synovium in patients with rheumatoid arthritis." (PMID 22235377, 2012). "Furthermore, as a secondary objective, we determine whether the CX3CL1/CX3CR1 axis could be considered complementary to clinical parameters to distinguish between periodontitis and rheumatoid arthritis (RA) and/or systemically healthy subjects." (PMID 38415821, 2024). "Interestingly, our analysis of the gene expression profile of NKG2D+ CD4+ T-cells revealed an increased expression of the two receptors, CX3CR1 and CKMLR1, both of which have been suggested to be involved in the pathology of rheumatoid arthritis." (PMID 22870231, 2012). "Elevated tissue and serum expression of CX3CR1 and CX3CL1 can be observed in rheumatoid arthritis (RA) and Sjogren's syndrome, affirming this chemokine participation in recruiting inflammatory cells in target organs." (PMID 39392260, 2024).
prostate carcinoma (23 papers, 2011 to 2025). A carcinoma that arises from epithelial cells of the prostate gland. "CX3CR1 on CD14+ CD16− monocyte was identified through IVW analysis to be positively associated with the risk of prostate cancer (OR = 1.0024, 95%CI:1.0007–1.0040, p = 0.0060)." (PMID 38566827, 2024). "The findings in this study revealed that enhanced expression of Cx3cr1 after Klf5KR knockin in Pten-deficient prostate cancer is an endogenous molecular mechanism by which FGFR1 signaling is activated by its paracrine ligand FGF9." (PMID 38781024, 2024). "Upregulation of FGF9 and CX3CR1 is associated with FGFR1 activation in Pten-deficient human prostate cancer." (PMID 38781024, 2024). "Collectively, FGF9 and CX3CR1 depended on each other to activate FGFR1 in PTEN-deficient prostate cancer." (PMID 38781024, 2024). "The expression level of Cx3cr1 was increased by Klf5KR knockin in Pten-deficient prostate cancer, as suggested by RNA-Seq and confirmed by IHC staining of prostate tissues from PBCrePten–/–Klf5KR/KR and PBCrePten–/–Klf5+/+ mice." (PMID 38781024, 2024). "The addition of AZD8797 and JMS-17-2 selectively suppressed the growth of organoids with deAc-KLF5, indicating that induced Cx3cr1 by Klf5KR knockin is an essential mechanism by which Pten-deficient prostate cancer cells have an advantage in tumor growth." (PMID 38781024, 2024). "Inhibition of CX3CR1 sensitized PTEN-deficient prostate cancer to the AKT inhibitor capivasertib." (PMID 38781024, 2024). "We further focused on p-AKT+ samples to determine whether FGF9 is an active ligand of FGFR1 and whether CX3CR1 is required for FGFR1 activation in PTEN-deficient prostate cancer." (PMID 38781024, 2024). "We therefore further evaluated whether FGF9 and CX3CR1 are associated with FGFR1 activation in PTEN-deficient human prostate cancer." (PMID 38781024, 2024). "We therefore used a patient-derived xenograft (PDX) model with PTEN deficiency to determine whether inhibition of CX3CR1 could sensitize prostate cancer cells to capivasertib." (PMID 38781024, 2024). "CX3CR1 inhibition sensitizes PTEN-deficient prostate cancer to the AKT inhibitor capivasertib." (PMID 38781024, 2024). "Notably, FGF9 and CX3CR1 depended on each other to activate FGFR1 in PTEN-deficient human prostate cancer." (PMID 38781024, 2024). "CX3CL1/CX3CR1 is an important factor in bone metastasis of prostate cancer because prostate cancer cells express CX3CR1 and bone marrow endothelial cells and osteoblasts express CX3CL1." (PMID 40508161, 2025). "The findings in this study provide a clinical rationale for the combined use of the CX3CR1 inhibitor JMS-17-2 and the p-AKT inhibitor capivasertib in PTEN-deficient prostate cancer." (PMID 38781024, 2024). "In patients with prostate cancer, high expression levels of CX3CR1 were required for FGF9 to activate FGFR1 signaling, and CX3CR1 was positively associated with FGFR1 activation under FGF9 secretion." (PMID 38781024, 2024). "In vivo animal models showed that the overexpression of CX3CR1 induced the spinal metastasis of prostate cancer via the FKN/steroid receptor coactivator (Src)/focal adhesion kinase (FAK) signaling pathway." (PMID 38731899, 2024). "The organoid assay was further used to evaluate the effects of CX3CR1 inhibitors on prostate cancer progression in vitro." (PMID 38781024, 2024). "CX3CR1 inhibition blocked FGFR1 activation triggered by FGF9 and sensitized PTEN-deficient prostate cancer to the AKT inhibitor capivasertib." (PMID 38781024, 2024). "Increased FGF9 and upregulated CX3CR1 cooperate to activate FGFR1 signaling, which leads to the progression of PTEN-deficient prostate cancer." (PMID 38781024, 2024). "KLF5 acetylation has a role in reprogramming cancer-associated fibroblasts and contributes to the synergism between AKT and CX3CR1 inhibitors in a prostate cancer model." (PMID 38781024, 2024).
prostate carcinoma (continued). "Human bone marrow endothelial cells and differentiated osteoblasts were found to express fractalkine, whereas human prostate cancer cells overexpressed its specific receptor CX3CR1." (PMID 39459070, 2024). "Interruption of Klf5 acetylation, on the one hand, signals iCAFs to release FGF9 via TNF-α; on the other hand, deacetylation of Klf5 induces CX3CR1 expression in prostate cancer cells." (PMID 38781024, 2024). "CX3CL1’s unique receptor CX3CR1 is expressed by a wide variety of immune cells and tumor cells in malignancies such as multiple myeloma, metastatic pancreatic cancer, prostate cancer and lymphocytic leukemia." (PMID 37153002, 2023). "Prostate cancer spinal metastases express high levels of CX3CR1, and overexpression of CX3CR1 in prostate cancer cell lines promotes proliferation, migration, and invasion while inhibiting apoptosis." (PMID 36118530, 2022). "High CX3CR1 status resulted in resistance to docetaxel treatment, which is the standard-of-care chemotherapy for breast and prostate cancer." (PMID 36118530, 2022). "Follow up studies in prostate cancer cell lines show that they express CX3CR1, the receptor enhances migration in a scratch wound assay, and migration is dampened by CX3CR1 knock-down or by inhibitors of the Src/FAK pathway." (PMID 36118530, 2022). "An elevated expression level of its receptor, CX3CR1 (C-X3-C Motif Chemokine receptor 1), has been implicated in the development of PNI and earlier recurrence of numerous cancers, such as PC, gastric cancer, and prostate cancer." (PMID 33014792, 2020). "Under hypoxic conditions CX3CR1 expression is also increased by NF-κB as confirmed by research on prostate cancer cells." (PMID 32466280, 2020). "Prostate cancers have a high propensity to metastasize into regional lymph nodes, and their expression of CX3CR1 correlates positively with the metastatic proclivity." (PMID 29650776, 2018). "In this study, we have shown that CD9+ halos surround lymphatic vessels in human prostate cancer specimens and that EEV fractions promoted the migration of CX3CR1+ human PC3-ML prostate cancer cells in a CX3CL1-dependent manner." (PMID 29650776, 2018). "Prostate carcinomas frequently invade lymphatic vessels and form metastases in a CX3CR1-dependent manner." (PMID 29650776, 2018). "In particular, CX3CR1 expression in pancreatic and prostate cancer cells increases invasiveness and metastasis to neuronal tissues." (PMID 28791023, 2017). "Similar regulation of another chemokine receptor, chemokine (C-X3-C motif) receptor 1 (CX3CR1), is also shown in prostate cancer and pancreatic ductal adenocarcinoma cells to mediate their migration and invasion." (PMID 23241400, 2012). "We were the first to report that prostate cancer cells express CX3CR1 and that these cells, under dynamic-flow conditions, adhere to human bone marrow endothelial cells in a FKN-dependent manner." (PMID 21933397, 2011). "Furthermore, CX3CR1 expression was significantly increased under hypoxic conditions and was involved in the migration and invasion of prostate cancer cells through the action of HIF-1 and NF-κB." (PMID 40508161, 2025). "Furthermore, overexpression of CX3CR1 induced spinal cord metastasis of prostate cancer in an in vivo mouse model." (PMID 40508161, 2025). "Consistently, DU 145 prostate cancer cells with KLF5KR also had increased CX3CR1 expression." (PMID 38781024, 2024). "Exposure to FKN may result in epithelial-to-mesenchymal transition (EMT) with enhanced CX3CR1+ cell migration, which is symptomatic of increased invasive and metastatic potential during prostate cancer progression." (PMID 38731899, 2024). "The FKN/CX3CR1 interaction may be crucial in the development of prostate cancer metastases to bone tissue." (PMID 38731899, 2024). "Activation of CX3CR1 causes EMT in pancreatic ductal adenocarcinoma and prostate cancer cells." (PMID 32466280, 2020).
prostate carcinoma (continued). "In addition, we have shown that CX3CR1 is expressed in a high percentage of prostate cancer tissues while human bone marrow supernatants contain soluble FKN, which is released from cells of the bone stroma through a mechanism regulated by androgens." (PMID 21933397, 2011). "Prostate cancer cells that express CX3CR1 adhere to human bone marrow endothelial cells and migrate toward a medium conditioned by osteoblasts, which secrete the soluble form of the chemokine contributing to the high likelihood of prostate cancer cells metastasizing to the skeleton." (PMID 21750716, 2011). "Thus, CX3CL1/CX3CR1 is involved in prostate cancer metastasis and may be a target for prostate cancer therapy." (PMID 40508161, 2025). "Thus, androgens could promote the extravasation of CX3CR1-expressing cancer cells along a fractalkine concentration gradient, indicating a potential role in prostate cancer bone metastasis." (PMID 39459070, 2024). "In prostate cancer, the combination of a CX3CR1 inhibitor and capivasertib, an AKT inhibitor, was shown to inhibit prostate cancer progression." (PMID 40508161, 2025). "CX3CL1/CX3CR1 induced EMT and migration and invasion of androgen-independent prostate cancer cells via TACE/TGF-α in several prostate cancer cell lines under hypoxic conditions." (PMID 40508161, 2025). "Knockdown of CX3CR1 or blockage of CX3CR1 by different chemical inhibitors (AZD8797 and JMS-17-2) effectively suppressed FGFR1 activation and the formation of prostate cancer organoids." (PMID 38781024, 2024). "The other chemokine receptor gene whose expression correlated with that of CXCR4 was CX3CR1, which is expressed in NK cells, subsets of monocytes, CD4+ and CD8+ T cells, as well as prostate cancer and various experimental cancers and cancer cell lines." (PMID 29088715, 2017). "Further in vitro experiments showed that CX3CL1 promoted BG1 cell proliferation through its binding to CX3CR1 as well as AKT activation, as previously reported for human prostate cancer cells." (PMID 21750716, 2011). "Functionally, knockdown of CX3CR1 suppressed the activation of FGFR1 signaling in DU 145 cells with KLF5WT and KLF5KR and attenuated the hyperactivation of FGFR1 signaling in KLF5KR-expressing prostate cancer cells." (PMID 38781024, 2024). "Furthermore, in human prostate cancer tissue assays, we detected p-AKT, FGF9, CX3CR1, and p-FRS2 with IHC staining." (PMID 38781024, 2024). "CX3CR1 in macrophages has been shown to modulate the secretion of proinflammatory cytokines including TNF-α, thus it is likely that the increase in TNF-α release in tumor cells was attributed to the higher level of CX3CR1 in Klf5KR prostate cancer cells." (PMID 38781024, 2024). "Previous studies have suggested oncogenic functions of CX3CR1 in prostate cancer, as the expression of CX3CR1 in prostate cancer epithelial cells directs their circulation to the bone, and CX3CL1/CX3CR1 enhance the migration and metastasis of prostate cancer cells." (PMID 38781024, 2024). "The mechanisms contributing to increased expression of CX3CR1 in hypoxic conditions may involve HIF-1-dependent and NF-κB-dependent signaling pathways, as shown in prostate cancer cells." (PMID 24270813, 2014).
experimental autoimmune encephalomyelitis (22 papers, 2005 to 2025). An autoimmune demyelinating disease of the central nervous system that is produced experimentally in animals by the injection of homogenized brain or spinal cord in Freund's adjuvant. "Induction of experimental autoimmune encephalomyelitis (EAE) on a mouse model of CX3CR1 hypofunction by replacement of the normal mo Cx3cr1 locus for the hu Cx3cr1-I249/M280 variant, revealed exacerbated functional signs of EAE, with more severe inflammation and neuronal loss." (PMID 37818457, 2023). "Additionally, CX3CR1-deficient mice could develop to a very severe experimental autoimmune encephalomyelitis." (PMID 35222428, 2022). "Early studies that utilized in situ hybridization demonstrated that the majority of Cx3CR1+ cells in the spinal cord of experimental autoimmune encephalomyelitis (EAE) rats were microglia." (PMID 39329765, 2024). "In an experimental autoimmune encephalomyelitis model, CX3CR1+ microglia-specific AhR deletion upregulated the activation of proinflammatory astrocytes and aggravated inflammation, indicating that microglial AhR suppresses astrocytic inflammation." (PMID 36797786, 2023). "Intriguingly, mice with a constitutive knockout of CX3CR1 exhibit more severe demyelination and neurological defects when subjected to cuprizone or experimental autoimmune encephalomyelitis." (PMID 34270934, 2021). "We carried out intravital FLIM in the brain stem of CerTN L15xLysM:tdRFP and CX3CR1:eGFP mice, in health and during experimental autoimmune encephalomyelitis (EAE)." (PMID 32426367, 2020). "During experimental autoimmune encephalomyelitis (EAE), CX3CR1 deficiency confers exacerbated disease defined by severe inflammation and neuronal loss." (PMID 30386211, 2018). "For instance, experimental autoimmune encephalomyelitis (EAE) and ischemia are associated with an induction of CX3CL1 and an accumulation of CX3CR1-expressing cells." (PMID 21167054, 2010). "An experimental autoimmune encephalomyelitis (EAE) model of MS was utilized to assess time dependent gene and protein expression changes of CX3CL1 and CX3CR1." (PMID 24175290, 2013). "Moreover, in a model of experimental autoimmune encephalomyelitis (EAE), CX3CR1/fractalkine axis specifically recruits NK cells into the brain." (PMID 28791023, 2017). "We further show that the increased disease severity in experimental autoimmune encephalomyelitis is not due to haplodeficiency of the Cx3cr1 locus." (PMID 27400748, 2016). "It has also been reported that the Ly6Clo CX3CR1+ monocytes do not enter the brain after experimental autoimmune encephalomyelitis and that tissue remodeling is regulated by microglia." (PMID 25469644, 2014). "Although qualitative in nature, this data reflects recent observations made following experimental autoimmune encephalomyelitis in CCR2-RFP/CX3CR1-GFP mice, where unlike the highly ramified microglia, MDMs were elongated or spindle shaped, smaller and rarely had processes." (PMID 30376851, 2018).